GRIA1 (glutamate ionotropic receptor AMPA type subunit 1)
Diseases named in the same sentence as GRIA1 in open-access papers (continued):
Sharing a sentence is not in itself a finding about the gene and the disease.
Huntington disease (2 papers, 2022). Huntington disease (HD) is a rare neurodegenerative disorder of the central nervous system characterized by unwanted choreatic movements, behavioral and psychiatric disturbances and dementia. "TBP, GRM5, and GRIA1 were co-enriched in Huntington’s disease pathway." (PMID 36561136, 2022). "Moreover, subunit 1 of AMPA receptor (GRIA1) was also downregulated in Huntington’s disease mice." (PMID 36523271, 2022). "We also report a downregulation of proteins involved in glutamatergic signalling in the hippocampus of Huntington’s disease mice: SHISA6, responsible for AMPA-type glutamate receptor immobilization at postsynaptic density, and glutamate receptor 1 (GRIA1, AMPA type)." (PMID 36523271, 2022).
insomnia (2 papers, 2022 to 2024). A sleep disorder characterized by difficulty in falling asleep and/or remaining asleep. "Additionally, two variants within the glutamate ionotropic receptor AMPA type subunit 1 (GRIA1) gene, rs13168358 and rs1461225, were associated with insomnia." (PMID 38890579, 2024).
lung carcinoma (2 papers, 2013 to 2022). "The results showed the difference in protein expression of the hub genes (GRIA1 and CLEC3B) in normal and lung cancer tissues." (PMID 35936688, 2022).
maturity-onset diabetes (2 papers, 2023 to 2025). "Furthermore, research has identified new links between the polymorphic loci in the GRIN1 gene (rs6293) and external eating behaviors in individuals with type 2 diabetes, as well as associations of the GRIK3 (rs534131) and GRIA1 (rs2195450) genes with diabetic retinopathy." (PMID 40740189, 2025).
mental disorder (2 papers, 2014 to 2022). A disease that has its basis in the disruption of mental process. "A similar occurrence can be observed regarding GRIA1, which has mostly associated with susceptibility to mental disorder and cancer." (PMID 36140831, 2022). "GRIA1 and GABRB2 are relevant to mental disorders supported by multiple evidences." (PMID 24901472, 2014).
Obesity (2 papers, 2021 to 2025). Accumulation of substantial excess body fat. "Three of the common DEGs altered by obesity in all NVU cell types (Slc44a5, Gria1, and Shisa6) play a key role in neurotransmission." (PMID 41310161, 2025).
thrombosis (2 papers, 2014 to 2019).
Arthritis (1 paper, 2017). Inflammation of a joint. "The expression of Gria1 and Gria2 encoding the glutamate receptors GluR1 and GluR2, as well as NMDA subunits (NR1, NR2A and NR2B) was relatively unaffected by arthritis." (PMID 28321113, 2017).
ataxia telangiectasia (1 paper, 2022). Ataxia-telangiectasia is the association of severe combined immunodeficiency (affecting mainly the humoral immune response) with progressive cerebellar ataxia. "Finally, we found a correlative decrease in human GRIA1 mRNA expression in the cerebellum of patients with ataxia-telangiectasia and spinocerebellar ataxia type 6 patient iPSC-derived Purkinje cells, pointing to the clinical relevance of glutamatergic system." (PMID 36064798, 2022).
Autoimmunity (1 paper, 2025). The occurrence of an immune reaction against the organism's own cells or tissues.
Cirrhosis (1 paper, 2026). A chronic disorder of the liver in which liver tissue becomes scarred and is partially replaced by regenerative nodules and fibrotic tissue resulting in loss of liver function. "Notably, gene hubs like Drd1, Gria1‐4, Grin1, Grin2b, Grm5, and GABAα receptor genes were also highly connected, mirroring gene expression patterns observed in liver fibrosis, cirrhosis, and hepatocellular carcinoma (HCC)." (PMID 41508419, 2026).
fibromyalgia (1 paper, 2023). A chronic disorder of unknown etiology characterized by pain, stiffness, and tenderness in the muscles of neck, shoulders, back, hips, arms, and legs. "It was reported that glutamate receptors, e.g., GRIA1, may be deregulated in fibromyalgia patients." (PMID 37065490, 2023).
fibrosis (1 paper, 2016). the formation of excess fibrous connective tissue in an organ or tissue in a reparative or reactive process. "Deeper analysis of differential gene expression over the dose-response range that results in sublethal vs. lethal pneumonitis/fibrosis, identified only three genes associated with the threshold for lethality in both strains- Retnla, Gria1, and Auts2." (PMID 27845360, 2016).
keloid (1 paper, 2025). An irregularly shaped, elevated mark on the skin caused by deposits of excessive amounts of collagen during wound healing. "RNA-seq data revealed that GRIN2D was significantly upregulated in keloids compared to healthy controls, with other receptors like GRIA1 and GRID1 also showing notable expression changes." (PMID 41562114, 2025).
learning disability (1 paper, 2023). A group of disorders that affect a person's ability to learn or process specific types of information which is in contrast to his/her apparent level of intellect. "From our RNA-Seq data, among the 11 differentially regulated high-confidence ASD risk genes, there are few, which display learning disability phenotypes, which include GRIA1, GRID2, and IGF1." (PMID 37486945, 2023).
manic episodes (1 paper, 2020). "Also, studies have reported that GRIA1 may regulate the circadian rhythms, through the regulation of Clock gene, which has been demonstrated to be disrupted in the ventral tegmental area of patients with BD, particularly in manic episodes." (PMID 32411272, 2020).
Neurodevelopmental delay (1 paper, 2022). "Additionally, only missense heterozygous variants have been reported within the current literature, and our index case is the first homozygous nonsense variant in GRIA1 causing a neurodevelopmental delay phenotype." (PMID 35675825, 2022).
osteosarcoma (1 paper, 2024). A usually aggressive malignant bone-forming mesenchymal neoplasm, predominantly affecting adolescents and young adults. "Six of these genes are increased (MYOM2, VEGFA, MUC1, IHH, GLI1 and GRIA1) and seven are decreased (VCAM1, EGFR, GPC3, IGF2, GNG12, GNGT1 and C3) in localized patients with poor prognosis that either relapse or die due to osteosarcoma." (PMID 38538763, 2024).
urothelial carcinoma (1 paper, 2022). A malignant neoplasm derived from the transitional epithelium of the urinary tract (urinary bladder, ureter, urethra, or renal pelvis). "Elevated GRIA1 mRNA levels are significantly associated with worse OS in patients with basal-like urothelial carcinomas." (PMID 36052170, 2022).
tumor (20 papers, 2009 to 2025). "KIF20A and GALNT2 were elevated, whereas GRIA1 expressions were suppressed in tumor tissues, compared with adjacent normal tissues." (PMID 36524130, 2022). "In the TCGA dataset, mRNA levels of four genes (CNIH1, KIF20A, GALNT2, and AP3S1) were highly expressed in tumor tissues, while GRIA1 levels were downregulated in tumor tissues." (PMID 36524130, 2022). "Since GRIA1 was downregulated in LUAD tumor tissues, CNIH1 and AP3S1 were selected for further studies." (PMID 36524130, 2022). "Apart from GRIA1, upregulated mRNA levels of CNIH1, KIF20A, GALNT2, and AP3S1 were observed in tumor tissues in these datasets." (PMID 36524130, 2022). "Compared with the GRIA1 gene, the biological role of the CLEC3B gene in tumor is more prominent." (PMID 35936688, 2022). "Among the M2 macrophage-related genes we finally screened, the biological function of the GRIA1 gene in LUAD tumor progression has not been revealed." (PMID 35936688, 2022). "Moreover, the presence of “anti-cancer” next to “pro-tumorigenic” within a single tumor only complicates the final conclusion regarding AP-2 role in that cancer (e.g. KRT14 vs GRIA1, SEZ6L, SLC12A5 for AP-2α within PAAD or NTSR1 vs PPEF1 for AP-2γ within LUAD)." (PMID 35361846, 2022).
cancer (12 papers, 2014 to 2025). A tumor composed of atypical neoplastic, often pleomorphic cells that invade other tissues. "We confirmed known gene interactions of PRPF8 and GRIA1 in testis and brain cortex, and observed a novel interaction of FGFR2, in breast and prostate, modulated by cancer risk-variants." (PMID 30545302, 2018). "In the 8-mRNA signature (KCNJ18, RPE65, GRIA1, LCN15, C11orf21, ANXA13, FSIP2 and KRT76), the expressions of some mRNAs have been reported to have significant associations with the survival in some cancers." (PMID 35675043, 2022). "These merged DMxDE datasets suggest some known or previously reported/suspected cancer genes [PR: SPARCL1, NQO1, CST1, MELK1, DPT, FAM83A, MMP9; GB: FOXM1, TFAP2, GREM1, ITGA8, GRIA1, SLIT3] as well as many previously unreported genes/loci." (PMID 26683690, 2015).
psychiatric disorder (12 papers, 2012 to 2024). A disorder characterized by behavioral and/or psychological abnormalities, often accompanied by physical symptoms. "In the PPI network of these Egr targets in the DG region, the top key nodes tightly associated with distinct psychiatric disorders and addictive behaviors in previous studies included Syt1, Stx1a, Dlg4, Cplx1, Gria1, Snap25, Rab3a, and Bdnf81,86–91." (PMID 37758941, 2023). "This hypothesis is in agreement with a previous study showing the association between the GRIA1 gene, that encode the GluR1 AMPAR, and psychiatric disorders." (PMID 27959333, 2016).
infection (6 papers, 2014 to 2023). The state of being infected such as from the introduction of a foreign agent such as serum, vaccine, antigenic substance or organism. "Notably, GRIA1, a regulator in glutamatergic signaling, and HSPA9, a stress-associated protein, were detected only in EVs from infected macrophages, suggesting specific roles in intercellular communication during infection." (PMID 33785616, 2021).
central nervous disease (1 paper, 2021). "There are several up-regulated genes within the hippocampus, such as BDNF, NPY2R, and Gria1, and downregulated genes such as Arc, which are well known in the neural plasticity and pathogenesis of central nervous disease and abnormal behavior." (PMID 34045967, 2021).
GRIA1 also shares sentences with these, for which no sentence is quoted: neurological diseases (16 papers); encephalitis (10); memory impairment (10); Hyperammonemia (8); status epilepticus (6); injury (4); mood disorder (4); neurodegenerative disease (4); neurodevelopmental disorder (4); neuropathic pain (4); alcohol (3); autoimmune encephalitis (3); brain injury (3); breast carcinoma (3); dementia (3); fragile X syndrome (3); ischemia (3); pancreatic cancer (3); temporal lobe epilepsy (3); amnesia (2); anxiety disorder (2); attention deficit-hyperactivity disorder (2); autism spectrum disorder (2); brain disorder (2); cardiovascular disease (2); cocaine addiction (2); colorectal cancer (2); Insulin resistance (2); melanoma (2); peripheral nerve injury (2).
A further 73 diseases each share a sentence with GRIA1 in 2 papers or fewer.